ANO1 (anoctamin 1)
Diseases named in the same sentence as ANO1 in open-access papers (continued):
Sharing a sentence is not in itself a finding about the gene and the disease.
metastatic cancers (1 paper, 2024). A carcinoma which has spread from the original site of growth to another anatomic site. "However, the mechanism behind the control of ANO1 expression in certain metastatic cancers has not been elucidated yet." (PMID 38773164, 2024).
migraine (1 paper, 2019). "This could explain why women exhibit a higher susceptibility to migraine, and suggests that potential interaction of TRPV1 and ANO1 in TG neurons may be involved in migraine initiation." (PMID 31336748, 2019).
Myocardial fibrosis (1 paper, 2025). "Studies have shown that ANO1 expression is significantly increased during myocardial fibrosis." (PMID 41210337, 2025). "However, the role of ANO1 in myocardial fibrosis is controversial." (PMID 41210337, 2025).
Opportunistic infection (1 paper, 2017). An infection that is caused by a pathogen that would generally not be able to cause an infection in a host with a normal immune system. "Serratia marcescens ano1 and ano2 had predicted virulence factors possibly involved in attacking parasites and/or causing opportunistic infection in mosquito hosts." (PMID 28861046, 2017).
oropharyngeal squamous cell carcinoma (1 paper, 2017). "Results from The Cancer Genome Atlas (TCGA) and an additional independent dataset of oropharyngeal squamous cell carcinoma (OPSCC) tumors reveal that, contrary to reports by prior studies, ANO1 expression is primary regulated by positively correlated CpG’s." (PMID 29123240, 2017).
papillary thyroid carcinoma (1 paper, 2019). "Immunofluorescence staining with an antibody against ANO1 revealed high expression of ANO1 in one ATC sample among 4 different patient-derived samples, while ANO1 expression was scarcely observed in all thyroid nodular hyperplasia and papillary thyroid carcinoma samples (each 20 samples)." (PMID 31489251, 2019). "Furthermore, ANO1-expressing cells in ATC tissue showed morphologically extended cell body shape compared to the shape of papillary thyroid carcinoma cells." (PMID 31489251, 2019).
prostate adenocarcinoma (1 paper, 2015). "Patch clamp measurement of whole-cell currents in PC-3 (human prostate adenocarcinoma derived) cells expressing high level of ANO1 showed that idebenone at 10 μM and 30 μM inhibits ATP-induced CaCCs chloride currents by ~54% and ~90%, respectively." (PMID 26196390, 2015).
Right ventricular hypertrophy (1 paper, 2025). In this case the right ventricle is more muscular than normal, causing a characteristic boot-shaped (coeur-en-sabot) appearance as seen on anterior- posterior chest x-rays. "Another research found that ANO1 facilitated PASMC proliferation, pulmonary arterioles remodelling and right ventricular hypertrophy, possibly via activating ERK1/2 in an MCT-treated hypertensive rat model." (PMID 41210337, 2025).
tongue cancer (1 paper, 2019). A malignant neoplasm affecting the tongue. "Alterations in ANO1, NUDCD1, PIK3CA defined survival in tongue cancer patients with nodal metastasis (node+ECS-), while EPS8 is a significant differential in node+ECS- laryngopharyngeal cancers." (PMID 31310629, 2019).
triple-negative breast carcinoma (1 paper, 2015). An invasive breast carcinoma which is negative for expression of estrogen receptor (ER), progesterone receptor (PR), and human epidermal growth factor receptor 2 (HER2). "The expression of Ano1 was significantly decreased in patients with triple-negative breast cancer (TNBC) (p = 0.033)." (PMID 25961581, 2015).
tumor (245 papers, 2009 to 2026). "Further studies reveal that ANO1 expression is closely linked to tumor subtypes, with high expression correlating with shorter survival and distant metastasis in HNSCC, whereas no prognostic significance is observed in HPV-positive HNSCC." (PMID 40356890, 2025). "ANO1 expression is upregulated in various GI cancers, involved in tumour invasion, metastasis, or drug resistance, and associated to poor prognosis in patients with these cancers." (PMID 40396170, 2025). "We constructed a diagnostic model for evaluating ANO1 mRNA or tumor biomarkers to compare their diagnostic ability." (PMID 31266974, 2019). "We constructed a logistic regression model for examining the diagnostic ability of ANO1 mRNA in comparison with conventional tumor markers, including CEA, CA199, and CA724." (PMID 31266974, 2019). "In our analysis of correlations between the mRNA expression level of ANO1 and clinical parameters, we found that ANO1 expression is associated with tumor size; the larger the tumor, the higher the positive rate of ANO1 expression." (PMID 31266974, 2019). "Expression levels of ANO1 were significantly associated with tumor size, mitotic count and risk levels." (PMID 27153560, 2016). "Tumor size, mitotic count and risk level were associated with ANO1 detection in resectable GIST patients." (PMID 27153560, 2016). "ANO1 expression was seen in the cytoplasm and cell membrane of the tumor cells, and was significantly associated with the location of tumors (P = 0.0201)." (PMID 27016410, 2016). "The expression levels of ANO1 and the positive rates of ANO1 were significantly higher in patients with large tumor size, high mitotic count and high risk." (PMID 27153560, 2016). "Notably, in HNSCC, both high ANO1 protein expression and gene amplification are associated with shorter survival, as ANO1 enhances tumor cell migration, and promotes distant metastasis." (PMID 40356890, 2025). "ANO1 upregulation has been linked to tumor progression and higher TNM staging in CRC." (PMID 40356890, 2025). "Notably, ANO1 serves as an independent prognostic biomarker closely associated with poor outcomes in multiple cancers, underscoring its clinical utility in tumor assessment and prognostic evaluation." (PMID 40356890, 2025). "ANO1 expression is associated with cell proliferation, migration, invasion, metastasis, tumor growth and survival." (PMID 33803266, 2021). "In addition to controlling proliferation and cell cycle progression, ANO1 expression is associated with resistance of apoptotic cell death in several tumor types." (PMID 33803266, 2021). "Tumor microenvironment may be one of the causes of ANO1 mRNA amplification in PBMCs of GIST patients." (PMID 31266974, 2019). "Moreover, a combined analysis with ANO1 mRNA and conventional tumor markers can significantly increase the diagnostic ability." (PMID 31266974, 2019). "Our results showed that ANO1 mRNA was significantly amplified in PBMCs, the average expression level and range of ANO1 mRNA in the blood were increased along with the expression of ANO1 in the tissues, and the extent of amplification of ANO1 was associated with tumor size." (PMID 31266974, 2019). "Several studies have indicated that ANO1 may be of clinical value as a diagnostic and prognostic biomarker and therapeutic target of tumours." (PMID 24316695, 2014). "Furthermore, ANO1 has been implicated to regulate tumor cell motility and metastasis via interaction with the cytoskeletal proteins of the ezrin/radixin/moesin family." (PMID 24599954, 2014). "Furthermore, the level of ANO1 overexpression is associated with tumor size." (PMID 40356890, 2025). "Furthermore, we elucidated the association between ANO1 and a range of neoplastic diseases." (PMID 40356890, 2025).
tumor (continued). "Therefore, ANO1 holds dual value as both a therapeutic target and a biomarker in neoplastic diseases, facilitating patient prognosis assessment, risk stratification, and clinical decision-making, thereby advancing precision medicine and personalized treatment strategies." (PMID 40356890, 2025). "However, how ANO1 inhibition exerts anti-tumor activity or causes apoptosis in cancer cells remains unknown." (PMID 29899325, 2018). "Thus, ANO1 is highly associated with tumor and its progression." (PMID 26811235, 2016). "In tumor cells, activated ANO1 promoted TGF-β production and release, which increased cancer-associated fibroblasts (CAFs) infiltration and inhibited accumulation of CD8+T cells, leading to immunotherapeutic resistance to anti-PD-1 antibody in GI cancers." (PMID 40396170, 2025). "Unexpectedly, ANO1 exhibits lower expression in highly invasive cancer cells while being more highly expressed in adherent tumor cells, which presenting a challenge for ANO1-targeted therapy." (PMID 40356890, 2025). "In HNSCC, ANO1-induced cancer cell proliferation and tumor growth are coupled with activation of extracellular-regulated kinases 1/2 (ERK1/2), and inhibition of ERK1/2 effectively reduces ANO1-driven cell proliferation." (PMID 40356890, 2025). "Discovered on GIST 1 (DOG-1; also known as ANO1) showed IHC positivity in all tumor samples for which information was available." (PMID 39853155, 2025). "Our results from the genetic perturbation of a CDDP-resistant HNSCC cell line model further support a direct role of Ano1 in mediating tumor progression and drug resistance." (PMID 39789065, 2025). "Role of ANO1/TMEM16A, a calcium-activated chloride channel, in apoptosis resistance and tumor immune escape." (PMID 39941737, 2025). "By immunohistochemistry (IHC), the tumor showed strong, diffuse positivity for DOG1 (ANO1) and CD117, and negativity for SMA, desmin, HMB45, Mel-A, CDK4, MDM2, S100, CKAE1/AE3, CK7, racemase, and PAX8." (PMID 40018405, 2025). "As research progresses, the molecular mechanisms by which ANO1 mediates tumour malignancy are becoming clearer." (PMID 40396170, 2025). "ANO1 also plays an important role in a variety of tumor infiltrating immune cells and regulating anti-tumor immune response in tumor microenvironment." (PMID 40396170, 2025). "Recent evidence indicates that in gastrointestinal tumors, ANO1 promotes tumor progression by inhibiting ferroptosis in a PI3K/Akt-dependent manner." (PMID 40356890, 2025). "In colorectal cancer (CRC), its high expression is associated with poor prognosis, and pharmacological inhibition of ANO1 suppresses tumour growth by downregulating Wnt/β-catenin signalling." (PMID 40806720, 2025). "A 83-fold higher tumor avidity for iodine was observed for a tenfold higher ANO1 expression in the tissue." (PMID 39982585, 2025). "Recent research suggests that ANO1 contributes to the development of an immunosuppressive tumor microenvironment (TME), driving cancer cell resistance to anti-PD-1 immunotherapy." (PMID 40356890, 2025). "The mechanisms by which ANO1 promotes the malignant behaviour of tumour cells are complex and primarily include the regulation of upstream noncoding RNAs and the activation of multiple downstream signalling pathways." (PMID 40396170, 2025). "Upregulated ANO1 expression in CRC is accompanied by downregulated expression of tumour-suppressing microRNAs including miR-144, miR-132, miR-9, and miR-18a." (PMID 40396170, 2025). "In CRC, dehydroandrographolide (DP) can significantly inhibit chloride ion currents in SW620 cells, reduce ANO1 protein expression, and suppress the activity and migration of tumour cells." (PMID 40396170, 2025). "Further exploration of the role of ANO1 in gastrointestinal cancer is crucial for advancing tumour diagnosis and treatment." (PMID 40396170, 2025). "ANO1 is also vital in modulating the tumour microenvironment through its effects on cell cycle or host’s immune response to tumours." (PMID 40396170, 2025).
tumor (continued). "In studies to date that have shown that ANO1 is overexpressed in multiple diseases and tumor types and contributes to the process of carcinogenesis." (PMID 38352864, 2024). "Bioinformatics analysis of the TCGA dataset was used to explore how ANO1 induces an immunosuppressive tumor microenvironment." (PMID 38352864, 2024). "Multiple studies have identified the effects of ANO1 on tumor cells in various types of cancer,however, its effects on PC and the TME of PC have rarely been studied." (PMID 38352864, 2024). "This study investigated the prognostic value of ANO1 and its correlation with the tumor microenvironment (TME) in PC." (PMID 38352864, 2024). "In fact, knocking-down or pharmacological inhibition of TMEM16A/ANO1 in tumor cells inhibited their proliferation by reducing EGFR activation and its downstream signaling pathways." (PMID 36979639, 2023). "ANO1 contributes to an immune‐suppressive tumor microenvironment and induces acquired resistance to anti‐PD‐1 immunotherapy, while ANO1 knockdown or inhibition enhances immunotherapeutic effectiveness and overcomes resistance to immunotherapy." (PMID 37341301, 2023). "ANO1 knockdown consistently reduced the number of metastatic tumor nodules in the abdominal cavity, liver, and lung, suggesting that ANO1 facilitates the growth and metastasis of GC." (PMID 37341301, 2023). "As a result, ANO1 contributes to an immune‐suppressive tumor microenvironment, while ANO1 knockdown can restore the immune activity in TIME." (PMID 37341301, 2023). "This work highlights ANO1's role in mediating tumor immune microenvironment remodeling and immunotherapeutic resistance, and introduces ANO1 as a promising target for GI cancers’ precision treatment." (PMID 37341301, 2023). "ANO1's positive rate was higher in nonresponders (52.9%, 9/17) than responders (35.5%, 11/31), while ANO1‐negative cases displayed more favorable dynamic changes of tumor volume and the best changes of tumor volume than ANO1‐positive cases." (PMID 37341301, 2023). "In CT26 CDX, the sensitized anti‐tumor effectiveness by combining ANO1 knockdown and anti‐PD‐1 antibody was also alleviated by the ferroptosis inhibitor liproxstatin." (PMID 37341301, 2023). "In immune‐intact mice CDXs, apart from inhibiting tumor growth, ANO1 knockdown also increased the anti‐tumor immune activity, marked by increased infiltration/expression of CD8+ T cells/IFN‐γ/TNF‐α/granzyme B/IL‐13 and reduced PD‐L1 expression." (PMID 37341301, 2023). "Both ANO1 knockdown and inhibitors evidently augmented the anti‐tumor effect of anti‐PD‐1 antibody against MC38/CT26 xenografts." (PMID 37341301, 2023). "For cell‐derived xenograft (CDX) models, ANO1 knockdown leaded to markedly lower in vivo tumor growth rate/weight at the final observation, and reduced IHC staining for proliferation marker Ki67 and vascular marker CD31 in stripped xenografts." (PMID 37341301, 2023). "Various molecules and Stimuli control the expression of ANO1, and the regulatory mechanism of ANO1 is different in tumor cells." (PMID 35734591, 2022). "In the TCGA-HNSC cohort, we observed the expression of 12 ion channel genes in tumor and normal tissues; ANO1, AQP9, BEST2, CHRNA5, and KCNJ15 were upregulated in HNSCC, while AQP1, AQP5, SCNN1G, and SCN4A were downregulated." (PMID 36389709, 2022). "Knockdown of ANO1 inhibited cell proliferation, induced cell apoptosis in breast and lung cancer cells, and reduced tumor growth in established cancer xenografts." (PMID 36033489, 2022). "Stable reduction of ANO1 expression enhanced cell motility and metastases, but decreased tumor proliferation in an orthotopic mouse model." (PMID 36033489, 2022). "The mRNA expression of SPINK1, DSG3, ANO1 were significantly increased in PAAD tumor tissue while GIMAP1 were significantly decreased compared with normal tissues." (PMID 33901011, 2021).
tumor (continued). "There was significant upregulation of ANO1 expression in tumor vs. dysplastic and healthy tissues (p < 0.0001 and p = 0.0315, respectively)." (PMID 34638224, 2021). "The downregulated gene GIMAP1, with a hazard ratio (HR) < 1, was regarded as a tumor suppressor, while the upregulated genes ANO1, DSG3, and SPINK1, with a HR > 1, were considered oncogenes." (PMID 33901011, 2021). "Because silencing of ANO1 in cancer cells with 11q13 amplification results in reduction of cell proliferation, migration, and tumor growth, we knocked down ANO1 using two different shRNA constructs in ANO1HIGH cell lines to study its role in HNSCC." (PMID 33803266, 2021). "Oppositely to TMEM156, TMEM173, and TMEM213, patients with higher ANO1 expression have a lower fraction of lymphocytes in the tumor microenvironment." (PMID 34638224, 2021). "It is a calcium-activated chloride channel (CaCC) named TAOS2, tumor expansion and overexpression-2, DOG1, ANO1." (PMID 33681289, 2021). "Other studies have investigated the role of anoctamin-1 (ANO1) positive circulating tumor cells as potential biomarker in GIST reporting a sensitivity of 64.2% and a specificity of 88.1%." (PMID 32284790, 2020). "Overall, these data point to a possible role for anoctamin-1 in modulating tumor immune infiltration." (PMID 33048845, 2020). "As VRAC controls survival of cells, the functional crosstalk with ANO1 is highly relevant for tumor biology." (PMID 30893776, 2019). "A logistic regression model utilizing ANO1 or conventional tumor markers was constructed for the diagnosis of GISTs." (PMID 31266974, 2019). "In this study, we found that ANO1 mRNA was amplified in PBMCs of GIST patients and ANO1 expression was associated with tumor size." (PMID 31266974, 2019). "Compared to Ano1, much less is known for other anoctamin paralogues regarding their potential role in proliferation and tumor development." (PMID 30893776, 2019). "In this study, we found that amplification of the ANO1 mRNA in PBMCs is correlated with tumor size of GISTs, and the average expression level and range of ANO1 mRNA in the blood are increased along with the expression of ANO1 in the tissues." (PMID 31266974, 2019). "In conclusion, our results indicate that ANO1 mRNA is a potential tumor marker for non-invasive diagnosis of GISTs." (PMID 31266974, 2019). "For diagnosing GISTs, ANO1 combined with CA724 or with all of the tumor markers had better AUC, sensitivity, specificity, and positive predictive value." (PMID 31266974, 2019). "By contrast, treatment with ANO1 shRNA1 resulted in a significant reduction in tumor volume, which was 96 ± 57 mm3 (n = 6), ~ 11% of the tumor volume in the control group." (PMID 29899325, 2018). "Overall expression of immunohistochemical markers in tumor cells were evaluated for the scoring for ANO1, MMP9, snail, and E-cadherin expression." (PMID 29416639, 2018). "To further confirm the role for ANO1 knockdown in tumor growth in vivo, we constructed lentiviral vectors expressing ANO1 shRNA1 for silencing ANO1 expression in PC-3 cells as reported in our previous investigations." (PMID 29899325, 2018). "Overexpression of the Ca2+-activated chloride channel ANO1/TMEM16A is implicated in tumorigenesis, and inhibition of ANO1 overexpression suppresses xenograft tumor growth and invasiveness." (PMID 29899325, 2018). "Despite limited data on the mechanism how ANO1 is involved in tumorigenesis, many previous reports demonstrate that inhibition of ANO1 is sufficient to inhibit tumor growth in vitro and in vivo." (PMID 29416639, 2018). "ANO1 amplification and overexpression contribute to tumor growth by activating EGF receptor and calmodulin-dependent-protein kinase II, and subsequently enhancing AKT and mitogen-activated protein kinase (MAPK) signaling." (PMID 29899325, 2018).